RNU6-164P (RNA, U6 small nuclear 164, pseudogene)
Gene: Small nuclear RNA gene on chromosome 5 (162,477,891 to 162,477,993, forward strand). Ensembl gene ENSG00000201474.
Homologues: Orthologues: chimpanzee U6 (98% identical), dog U6 (68% identical), rabbit U6 (64% identical). Paralogues in human: RNU6-16P (80% identical), RNU6-20P (80% identical), RNU6-820P (80% identical), RNU6-921P (80% identical), RNU6-144P (79% identical), RNU6-25P (79% identical), RNU6-29P (79% identical), RNU6-73P (79% identical), RNU6-1 (78% identical), RNU6-1011P (78% identical), RNU6-1035P (78% identical), RNU6-15P (78% identical), and 1286 more.